UMOD (uromodulin)
Diseases named in the same sentence as UMOD in open-access papers (continued):
Sharing a sentence is not in itself a finding about the gene and the disease.
Hypertension (continued). "Second, shared association patterns of uromodulin-associated genes with complex traits and diseases are plentiful and place the PRKAG2 and UMOD loci into the same context with respect to their associations with CKD, hypertension, and kidney stone disease." (PMID 35446786, 2022). "In conclusion, uromodulin-facilitated NKCC2 phosphorylation contributes to the hypertension phenotype, especially under low [Cl−] levels." (PMID 36140271, 2022). "Uromodulin, a urinary protein synthesized and secreted from the thick ascending limb (TAL) of the loop of Henle, is associated with hypertension through the activation of sodium reabsorption in the TAL." (PMID 36012675, 2022). "On a mechanistic level, salt sensitivity is an important factor in the pathophysiology of hypertension, and uromodulin is involved in salt reabsorption via the NKCC2 (Na+-K+-2Cl− cotransporter) on epithelial cells of the ascending limb of loop of Henle." (PMID 36378920, 2022). "Although several genes, including uromodulin (UMOD), shroom family member 3 (SHROOM3) and engulfment and cell motility 1 gene (ELMO1) have been strongly associated with CKD, their roles in hypertension and CV outcome are still unclear." (PMID 36360378, 2022). "Presence of hypertension decreased uromodulin’s expression systemically (p=0.018) and intracranially (p=0.007)." (PMID 33768217, 2021). "The relationship between systemic and intracranial uromodulin, age, high BMI and hypertension were assessed." (PMID 33768217, 2021). "Serum uromodulin levels decreased gradually as BP levels increased (34.6, 33.2, 27.8, and 25.0 ng/mL for subjects with normotension, high-normal, grade 1 hypertension, and grade 2 hypertension, respectively, Pfortrend < 0.001)." (PMID 34869624, 2021). "The relationship between systemic and intracranial uromodulin, high BMI, age and hypertension were found significant." (PMID 33768217, 2021). "Studies showed that uromodulin was correlated with various diseases, including hypertension, CKD, diabetic nephropathy, and diabetic-related aortic stiffness." (PMID 34782019, 2021). "In our study, uromodulin was found to be increased significantly in overweight patients, decreased significantly in older patients and decreased in those patients with hypertension." (PMID 33768217, 2021). "Uromodulin was increased significantly in overweight patients, decreased significantly in older patients, and decreased in patients with hypertension." (PMID 33768217, 2021). "In contrast, genome-wide association studies and animal models show an increased risk of arterial hypertension in uromodulin-increasing UMOD loci variants, and uromodulin has even been suggested to be a possible target for blood pressure control." (PMID 32764816, 2020). "Our data are in line with previous clinical studies involving participants at high cardiovascular risk or with cirrhosis, which reported a lower prevalence of arterial hypertension in participants with higher serum or plasma uromodulin values." (PMID 32764816, 2020). "In a GWAS on hypertension, the minor G allele of rs13333226 in the UMOD gene was associated with a lower risk of hypertension, reduced urinary uromodulin excretion, and better renal function." (PMID 31065383, 2019). "A GWAS for hypertension using an extreme case-control design identified a SNP in the 5′ region of uromodulin gene (UMOD), which is almost exclusively expressed in the thick ascending limb of the loop of Henle in the kidney." (PMID 29881931, 2018). "The role and mechanism of polymerization of uromodulin in hypertension and hypertensive pregnancy warrants further study in human subjects." (PMID 28348009, 2017). "Lots of studies revealed that the variants of UMOD were associated with different risk of CKD, cardiovascular disease, hypertension, and hyperuricemia, T allele of rs12917707 was associated with lower risk of CKD and ESRD." (PMID 27938332, 2016).
Hypertension (continued). "Uromodulin has been validated as a biomarker of hypertension and renal injury and has been found at higher levels in patients with hypertension, relative to healthy individuals." (PMID 27792191, 2016). "This protein is known to play a role in human diseases such as hypertension and kidney failure, but uromodulin’s biological purpose still remains elusive." (PMID 26673890, 2015). "Hyperuricemia, hypertension, decreased urinary uromodulin levels, tubulointerstitial nephropathy and progressive kidney disease are characteristics of these diseases." (PMID 23990922, 2013). "The newly discovered UMOD locus for hypertension has the potential to give new insights into the role of uromodulin in BP regulation and to identify novel drugable targets for reducing cardiovascular risk." (PMID 21082022, 2010). "The newly discovered UMOD locus for hypertension has the potential to give unique insights into the role of uromodulin in BP regulation and to identify novel drugable targets." (PMID 21082022, 2010). "In particular, the role of uromodulin in difficult-to-treat and treatment-resistant hypertension and in advanced cardiovascular conditions that are particularly susceptible to blood pressure such as stroke, ischaemic heart disease and heart failure requires further study." (PMID 39259220, 2024). "Additionally, proteins such as AGT, ALB, APOL1 and UMOD had the highest disease scores (76–100% confidence) for hypertension and CKD." (PMID 38402394, 2024). "This is exemplified by the genotype-directed clinical trial,97 which might transform and widen our treatment modalities for difficult-to-treat hypertension due to in-depth understanding of the uromodulin function dependent on genetic stratification." (PMID 36378920, 2022). "Uromodulin is a potential target for hypertension treatment via natriuresis." (PMID 36012675, 2022). "Additionally, some variants in the uromodulin gene promoter are associated with CKD and hypertension, and some variants with left atrial remodeling." (PMID 35053727, 2022). "More specifically, uromodulin regulates sodium uptake in the thick ascending limb of the loop of Henle by modulating the effect of tumor necrosis factor-α on NKCC2A expression, making UMOD an important determinant of blood pressure control and a candidate gene for essential hypertension." (PMID 35053727, 2022). "Previous animal studies showed that uromodulin may be involved in BP regulation and the development of hypertension." (PMID 34869624, 2021). "In addition, our study is the first to explore serum uromodulin levels in different hypertension subtypes." (PMID 34869624, 2021). "Serum uromodulin levels decreased gradually as BP levels increased (34.6, 33.2, 27.8, and 25.0 ng/mL for subjects with normotension, high-normal, grade 1 hypertension, and grade 2 hypertension, respectively)." (PMID 34869624, 2021). "In conclusion, our study based on open datasets suggests a potentially detrimental impact of high levels of uromodulin on the development of hypertension; which is the first time this has been shown to be consistent with the observational study and basic experimental study." (PMID 34540925, 2021). "Although UMOD has been linked to hypertension and regulation of salt reabsorption in the tubules, the mechanisms underpinning the influence of dietary salt on UMOD excretion have not been explored." (PMID 34870708, 2021). "As such we explored a reverse question, i.e. whether salt (and/or hypertension) could modulate UMOD from expression to excretion, and if so, whether there is a difference between normotensive and chronic hypertensive conditions." (PMID 34870708, 2021). "The correlation between uromodulin and hypertension was first disclosed in 1998." (PMID 34540925, 2021). "However, the biological role of UMOD in the pathogenesis of hypertension and kidney diseases is still elusive." (PMID 34870708, 2021). "A previous clinical study also has shown a link between UMOD gene and hypertension." (PMID 34869624, 2021).
Hypertension (continued). "We found that serum uromodulin showed a linear decrease from normotension to grade 2 hypertension, suggesting that circulating uromodulin may be a novel marker for identifying stages of hypertension." (PMID 34869624, 2021). "It is conceivable that hypertension-related microvascular injury may impair tubular function and thus decrease uromodulin secretion." (PMID 32764816, 2020). "High expression of uromodulin could activate the renal sodium cotransporter NKCC2 which induced hypertension in UMOD transgenic mouse model." (PMID 27938332, 2016). "The association of genetic variants at PRKAG2 with higher risk for CKD and hypertension as well as lower risk for kidney stone disease suggests a biological link between PRKAG2 and UMOD and suggest that PRKAG2 represents another target to modulate uromodulin-mediated risk of CKD." (PMID 35446786, 2022). "In addition, large GWAS metaanalyses have identified polymorphisms in the UMOD promoter that are associated with a lower concentration of uromodulin but higher eGFR, a lower risk for CKD, lower blood pressure, a lower risk of hypertension, and left atrial remodeling." (PMID 34568379, 2021). "The associations of UMOD gene variants with hypertension susceptibility may be linked to the role of uromodulin in regulating sodium-potassium-chloride cotransporter NKCC2 in the TAL and suggest that uromodulin is a potential therapeutic target for hypertension." (PMID 34869624, 2021). "Furthermore, our results may further suggest that uromodulin might serve as a new therapeutic target for hypertension management." (PMID 34540925, 2021). "The exclusive expression of uromodulin in TAL, where physiologically crucial mechanisms of sodium handling are located, suggests that alterations of some of these mechanisms in G allele carriers may underlie their lower risk of hypertension." (PMID 21082022, 2010). "However, functional studies are needed to clarify the renal mechanisms by which the UMOD gene may affect hypertension and renal sodium handling." (PMID 21082022, 2010). "Proteins including AGT, ALB, APOL1, and UMOD had the highest disease scores (76–100% confidence) for CKD and hypertension." (PMID 38402394, 2024). "In 2018, the GWAS catalog found seven candidate genes with an established pathophysiological role in hypertension, namely ACE1, ACE2, ADRB1, ADRB2, MME, CACNA2D2, and UMOD." (PMID 36902588, 2023). "Interestingly, genetic associations with antibody-based circulating uromodulin at the PRKAG2 and UMOD/PDILT loci shared a very similar pattern of colocalization with numerous kidney-related traits (creatinine, cystatin C, urea, eGFR, CKD, urinary calculus, DBP, SBP, hypertension)." (PMID 35446786, 2022). "Hypertension can contribute to an AKI by decreasing perfusion to the kidney, therefore decreasing kidney function and uromodulin production." (PMID 33768217, 2021). "However, we found that associations between rs11864909 and eGFR or serum uromodulin were more prominent among participants with higher urinary ACR (≥300 mg/g), which represents advanced kidney injury and is highly correlated with long-term hypertension and diabetes." (PMID 34828293, 2021). "In our study, subjects with hypertension had significantly lower serum uromodulin levels than those without hypertension." (PMID 34869624, 2021). "To date, mouse models such as UMOD knock-out, transgenic overexpression model and hepsin knock-out, all lacking a background of hypertension, were used to dissect the role of UMOD in the pathogenesis of (predominantly salt-sensitive) hypertension." (PMID 34870708, 2021). "Uromodulin was found to be decreased in patients with hypertension compared to patients without hypertension which is a similar finding to a study done in 2020 demonstrating an inverse relationship with serum uromodulin and arterial hypertension." (PMID 33768217, 2021).
Hypertension (continued). "Most of these predictors (except for serum concentrations of cystatin C, NGAL, and uromodulin) were independent of age, diabetes duration, the presence of hypertension, heart failure, and the treatment with renin-angiotensin-aldosterone system inhibitors." (PMID 30158836, 2018). "More recently, variants in the uromodulin (UMOD) gene have been shown to be associated with GFR and CKD independent of age, sex, hypertension, and diabetic status." (PMID 20222955, 2010).
autosomal dominant tubulointerstitial kidney disease (44 papers, 2005 to 2026). "Mutations in the UMOD gene are recognised as important pathogenic factors in autosomal dominant tubulointerstitial kidney disease (ADTKD)." (PMID 41531277, 2026). "Similar results were found in a mouse model of autosomal dominant tubulointerstitial kidney disease due to uromodulin mutations (ADTKD-UMOD), in which cGAS was activated by cytosolic mtDNA." (PMID 40264103, 2025). "Uromodulin in urine was discovered several decades ago but came into the spotlight after the description of mutations in its encoding gene UMOD causing renal Mendelian disease (autosomal dominant tubulointerstitial kidney disease)." (PMID 39061561, 2024). "Autosomal dominant tubulointerstitial kidney disease due to uromodulin (ADTKD-UMOD) is an inherited kidney disease characterized by mutations in the UMOD gene with an autosomal dominant mode of inheritance." (PMID 39199307, 2024). "Heterozygous variants in the calcium-sensing receptor gene CASR (pLI = 0.05) can cause hypocalciuric hypercalcemia while autosomal-dominant tubulointerstitial kidney disease can be caused by variants in UMOD (pLI = 0), MUC1 (pLI = 0.02) or REN (pLI = 0)." (PMID 39099563, 2024). "Mutations in the gene encoding UMOD believed to cause autosomal dominant tubulointerstitial kidney disease (ADTKD) are reported to be a common cause of CKD7." (PMID 38609491, 2024). "Missense mutations in the uromodulin (UMOD) gene cause autosomal dominant tubulointerstitial kidney disease (ADTKD), one of the most common monogenic kidney diseases." (PMID 37885358, 2023). "Mutations in the UMOD gene are the most common cause of autosomal dominant tubulointerstitial kidney disease, resulting in progressive CKD, early onset hyperuricemia and gout." (PMID 35456398, 2022). "Mutation in the genes encoding uromodulin (UMOD) is responsible for autosomal dominant tubulointerstitial kidney disease, previously termed as familial juvenile hyperuricemic nephropathy or medullary cystic kidney disease." (PMID 36012675, 2022). "UMOD is the first identified and the most commonly mutated gene that causes autosomal dominant tubulointerstitial kidney disease (ADTKD)." (PMID 36140366, 2022). "UMOD mutations play crucial roles in congenital urolithiasis, hereditary hyperuricemia/gout, and medullary cystic kidney diseases." (PMID 29361765, 2018). "Multiple names have been proposed for this group of disorders, including medullary cystic kidney disease, familial juvenile hyperuricemic nephropathy, and uromodulin associated kidney disease." (PMID 29513881, 2018). "Importantly, the phenotype of TAL-specific Myh9/Myh10 kO mice shares striking similarity to patients with autosomal dominant tubulointerstitial kidney disease associated with rare mutations in the UMOD gene (ADTKD-UMOD)." (PMID 39986266, 2025). "Furthermore, UMOD (P07911) was previously associated with medullary cystic kidney disease, familial juvenile hyperuricemic nephropathy, and glomerulocystic kidney disease." (PMID 39237660, 2024). "Additionally, rare UMOD mutations can cause autosomal dominant tubulointerstitial kidney disease, further implicating uromodulin in renal pathology." (PMID 39728069, 2024). "Misfolded protein aggregates may cause toxic proteinopathy, including autosomal dominant tubulointerstitial kidney disease due to uromodulin mutations (ADTKD-UMOD), a leading hereditary kidney disease." (PMID 37838725, 2023). "Medullary cystic kidney disease type 2 (MIM 603860) and familial juvenile hyperuricemic nephropathy (MIM 162000) are autosomal dominant tubulointerstitial kidney diseases that are due to UMOD gene mutations and are collectively called uromodulin-associated kidney disease (UAKD)." (PMID 30175088, 2018). "Autosomal dominant tubulointerstitial kidney disease (ADTKD) due to uromodulin mutations is a hereditary kidney disease causing renal fibrosis." (PMID 37838725, 2023).
autosomal dominant tubulointerstitial kidney disease (continued). "Furthermore, rare mutations in UMOD are causing autosomal dominant tubulointerstitial kidney disease (ADTKD-UMOD), a gain of toxic function disorder due to abnormal accumulation of mutant uromodulin aggregates in the TAL, leading to kidney fibrosis and CKD12,13." (PMID 31863061, 2019). "Autosomal dominant tubulointerstitial kidney disease caused by mutations in uromodulin gene (ADTKD-UMOD) is a spectrum of hereditary renal disorders, characterized by early-onset hyperuricemia, gout and progressive nephropathy." (PMID 29569962, 2018). "However, the mechanisms of renal fibrosis are incompletely understood and we therefore explored these by establishing a mouse model for a renal tubular disorder, referred to as autosomal dominant tubulointerstitial kidney disease (ADTKD) due to missense uromodulin (UMOD) mutations (ADTKD-UMOD)." (PMID 28325753, 2017). "Medullary cystic kidney disease (recently named tubulointerstitial kidney disease TKD), caused by mutations in MUC1 and UMOD, is considered the autosomal dominant NPHP, with a later onset than the recessive form." (PMID 34204582, 2021). "Genes of UMOD, HNF1B, MUC1, REN and SEC61A1 were reported to be associated with autosomal dominant tubulointerstitial kidney disease (ADTKD)." (PMID 33574344, 2021). "To date, mutations in UMOD, HNF1B, REN and MUC1 have been shown to cause autosomal dominant tubulointerstitial kidney disease (ADTKD)." (PMID 28267784, 2017). "Heterozygous mutations in the genes encoding uromodulin (UMOD), hepatocyte nuclear factor 1β (HNF1B), renin (REN) and mucin-1 (MUC1) can result in autosomal dominant tubulointerstitial kidney disease (ADTKD)." (PMID 28701203, 2017). "Some mutations in UMOD can cause autosomal dominant tubulointerstitial kidney disease (ADTKD), leading to the acummulation of mutant uromodulin in the endoplasmic reticulum of tubular cells, causing decresed levels of urinary uromodulin and tubulointerstitial injury." (PMID 35722493, 2022). "Mutations in the uromodulin (UMOD) gene cause autosomal dominant kidney diseases, medullary cystic kidney disease 2 (MCKD2), and familial juvenile hyperuricemic nephropathy (FJHN), which present with juvenile onset of polyuria, hyperuricemia, gout, and progressive nephropathy." (PMID 31065383, 2019). "‘Autosomal dominant tubulointerstitial kidney disease – UMOD’ (ADTKD-UMOD) is caused by impaired maturation and secretion of mutant uromodulin (UMOD) in thick ascending limb of Henle loop (TAL) cells, resulting in endoplasmic reticulum (ER) stress and unfolded protein response (UPR)." (PMID 28220896, 2017). "In addition to the association of UMOD expression with CKD progression identified in GWAS, UMOD has also been identified as a gene responsible for Mendelian forms of kidney diseases, such as familial juvenile hyperuricemic nephropathy (FJHN) and medullary cystic kidney diseases (MCKD)." (PMID 30868372, 2019).